HLA-DRA (major histocompatibility complex, class II, DR alpha)
Diseases named in the same sentence as HLA-DRA in open-access papers (continued):
Sharing a sentence is not in itself a finding about the gene and the disease.
Parkinson disease (4 papers, 2012 to 2025). A progressive degenerative disorder of the central nervous system characterized by loss of dopamine producing neurons in the substantia nigra and the presence of Lewy bodies in the substantia nigra and locus coeruleus. "However, the most significant allelic differences between Parkinson’s disease (PD) and healthy cases after Bonferroni corrections were detected only for the expressed HLA-DRA*01:01:01 and -DQA1*03:01:01 alleles and the NR_SVA_381 genotype." (PMID 39336776, 2024).
ulcerative colitis (4 papers, 2013 to 2025). An inflammatory bowel disease involving the mucosal surface of the large intestine and rectum. "In addition, HLA-DRA gene polymorphisms are associated with the clinical course and long-term prognosis of ulcerative colitis." (PMID 36132072, 2022).
Alzheimer disease (3 papers, 2020 to 2024). A progressive, neurodegenerative disease characterized by loss of function and death of nerve cells in several areas of the brain leading to loss of cognitive function such as memory and language. "Although until now there is no report about the function and mechanism of HLA-DRA in osteosarcoma, previous studies have shown that HLA-DRA is involved in the evasion of the virus from the immune system and Alzheimer’s disease." (PMID 32665038, 2020).
chronic rhinosinusitis (3 papers, 2017 to 2024). Chronic form of sinusitis. "HLA-DRA has been associated with chronic rhinosinusitis with nasal polyps in previous studies and HLCS, BICD2, VSIR and SLC5A1 may be new targets for future research." (PMID 29253858, 2017). "Furthermore, based on the results of Phe‐MR analysis, it is suggested that lower expression of HLA‐DRA may contribute to a decreased risk of certain other disorders, including hematuria, chronic sinusitis, hyperlipidaemia, and inflammatory spondyloarthropathy." (PMID 38644354, 2024). "Comparisons with data from expression quantitative trait loci showed the most skewed allelic distributions in cases with chronic rhinosinusitis with nasal polyps compared with controls for the genes HLCS, HLA-DRA, BICD2, VSIR and SLC5A1." (PMID 29253858, 2017). "Our study indicates that HLCS, HLA-DRA, BICD2, VSIR and SLC5A1 could be involved in the pathogenesis of chronic rhinosinusitis with nasal polyps." (PMID 29253858, 2017). "This study suggests that HLA-DRA as well as four additional genes; HLCS, VSIR, BICD2 and SLC5A1, which have not been previously identified as associated with chronic rhinosinusitis with nasal polyps, could be important for the development of this disease." (PMID 29253858, 2017).
inflammatory bowel disease (3 papers, 2016 to 2022). A spectrum of small and large bowel inflammatory diseases of unknown etiology. "The HLA-DRA locus is associated with rosacea as well as with other inflammation-associated disorders, such as inflammatory bowel diseases including ulcerative colitis, Crohn’s disease, and celiac disease." (PMID 27649161, 2016).
leukemia (3 papers, 2014 to 2018). A malignant (clonal) hematologic disorder, involving hematopoietic stem cells and characterized by the presence of primitive or atypical myeloid or lymphoid cells in the bone marrow and the blood. "Eight genes (BAALC, CD14, CD34, CD74, DNTT, HLA-DRA, IRF8, and MN1) were all associated with “leukemia” (P = 1.15 × 10−4), “acute myeloid leukemia” (P = 9.37 × 10−3), and “proliferation of myeloid cells” (P = 0.044)." (PMID 26517675, 2015). "Finally, knockdown of HLA-DRA in THP-1 leukemia cells, LNX2 in BDCM cells, and SMC2 and RIS1 in both THP1 and BDCM cells also desensitized the cells to AraC, results that were also consistent with our association results." (PMID 24483146, 2014).
lung cancer (3 papers, 2019 to 2024). A malignant neoplasm involving the lung. "Additionally, HSD11B1 and HLA-DRA linked hypertension, diabetes, and obesity; UCHL1 linked hypertension, obesity, and lung cancer; LENG8 and HSPA1L linked diabetes, obesity, and lung cancer." (PMID 36685671, 2023).
lymphoma (3 papers, 2013 to 2023). A malignant (clonal) proliferation of B- lymphocytes or T- lymphocytes which involves the lymph nodes, bone marrow and/or extranodal sites. "We also found that a potential risk SNP (rs3135394) which is in the HLA-DRA promoter region might play an important role that determining the causal associations between SS and prostate cancer, endometrial cancer, and lymphomas." (PMID 37715206, 2023). "HLA-DRA, a candidate risk gene, might provide a novel point for the causal associations between SS and prostate cancer, endometrial cancer, and lymphomas." (PMID 37715206, 2023).
neuroblastoma (3 papers, 2015 to 2022). Neuroblastoma (NB) is the most common solid, extracranial childhood tumor. "To address the clinical effect of the HLA Class II positive cells on neuroblastoma cells, we examined the effect of HLA-DRA, -DRB1, -DPA1 and -DPB1 expressions on survival of high-risk neuroblastoma patients." (PMID 35525858, 2022).
Obesity (3 papers, 2021 to 2023). Accumulation of substantial excess body fat. "A direct comparison of profiles at T1 and T3 shows a lack of remodeling within promoter and enhancer regions that regulate cytokine-signaling (TNF), myeloid cell activation (CD80), and immune effector process (HLA-DRA) in monocytes from subjects with obesity." (PMID 34195568, 2021). "The hub genes calculated by Cytoscape software are MNDA (score 320), CYBB (score 314), CD86 (score 312), FCGR2C (score 242), NCF2 (score 240), LCP2 (score 182), TLR8 (score 148), HLA-DRA (score 54), LCP1 (score 30), and PTPN22 (score 8), which are considered to be associated with obesity-related AF." (PMID 36671813, 2023). "Specifically, we detected down-regulation of HLA-DRA (1.38-fold), STAT1 (1.3-fold), TNFSF10 (1.7-fold), and FCGR3A (fold reduction 1.65) with pregravid obesity." (PMID 34195568, 2021).
osteoarthritis (3 papers, 2022 to 2024). A noninflammatory degenerative joint disease occurring chiefly in older persons, characterized by degeneration of the articular cartilage, hypertrophy of bone at the margins and changes in the synovial membrane. "The expression levels of TCA1, TLR7, MMP9, CXCL10, CXCL13, HLA-DRA, and ADIPOQSPP1 were significantly higher in the IL-1β-induced group than in the osteoarthritis group in an in vitro qPCR experiment." (PMID 35734177, 2022).
pancreatic cancer (3 papers, 2021 to 2024). "Pandha and colleagues reported that the downregulation of MHC-I molecules was observed in pancreatic cancer, whereas HLA-DRA in MHC-II molecules was upregulated." (PMID 34073722, 2021). "Of these, three upregulated genes (HIST2H2AA3, LUZP6 and HLA-DRA) in exosomes also showed the same pattern in pancreatic tumors vs. normal pancreas tissue." (PMID 34073722, 2021). "Using the levels of the three genes (HIST2H2AA3, LUZP6 and HLA-DRA) in exosomes as a signature, we obtained a high sensitivity and specificity (accuracy) in distinguishing patients with pancreatic cancer from healthy controls and from those with chronic pancreatitis in an independent study." (PMID 34073722, 2021). "As reported, c8 was defined as antigen-presenting CAFs (CAFap) that overexpressed ACTA2, HLA-DRA, and CD74 55 and was enriched in pancreatic cancer." (PMID 36333338, 2022). "Random-effects meta-analysis results showed that the levels of HIST2H2AA3 showed a significant difference between pancreatic cancer and normal pancreas tissues, but those of LUZP6 and HLA-DRA did not." (PMID 34073722, 2021). "Using TCGA pancreatic cancer data, we found that between KRAS wild-type and mutants, there was a significant difference in the HIST2H2AA3 expression level (p = 0.001), but not in that of LUZP6 (p = 0.5) or HLA-DRA (p = 0.06)." (PMID 34073722, 2021).
prostate carcinoma (3 papers, 2019 to 2025). A carcinoma that arises from epithelial cells of the prostate gland. "In prostate cancer, HLA-DRA+ apCAFs have been proposed as potential mediators of immune escape." (PMID 41514658, 2025). "Recent prostate cancer single-cell and spatial transcriptomic analyses (e.g., by Han Lin and colleagues) classified CAFs into iCAF, myCAF, and apCAF states, and identified C11_HLA-DRA as a representative apCAF cluster." (PMID 41514658, 2025).
septic shock (3 papers, 2013 to 2020). Shock caused by infection; frequently caused by gram negative bacteria, although some cases have been caused by other bacteria, viruses, fungi, and protozoa; characterized by fever, chills, tachycardia, tachypnea, and hypotension. "In a cohort of 93 septic shock patients alive three days after shock, mHLA-DR was measured by flow cytometry and CD74, HLA-DRA, HLA-DMA, HLA-DMB and CIITA mRNA levels were evaluated in whole blood by qRT-PCR." (PMID 24321376, 2013).
Allergy (2 papers, 2015 to 2018). An allergy is an immune response or reaction to substances that are usually not harmful. "However, of importance for the implementation of control programmes in Africa, it has been suggested that analysis of gene variants of HLA-DRA and the HLA-DRA|HLA-DRB5 inter-region, which may be significant predictors of allergy to penicillin, should occur in African populations." (PMID 25962944, 2015).
autoimmune disorders (2 papers, 2023 to 2025). "Genetic risk factors have been newly identified for Sjögren’s syndrome, including IRF5, STAT4, CXCR5, IL12A, HLA-DRA, and BLK, which are linked to autoimmune disorders as well." (PMID 40136761, 2025). "HLA-DRA and HLA-DRB alleles encode HLA-DR antigen, acting as regulatory molecule involved in autoimmunity." (PMID 36926335, 2023).
diffuse large B-cell lymphoma (2 papers, 2020 to 2023). "Both at transcription and protein levels, reduced expression of HLA-DRA has been shown to predict poor overall survival and progression-free survival in diffusive large B-cell lymphoma." (PMID 32256213, 2020).
metastatic melanoma (2 papers, 2021 to 2022). A melanoma that has spread from its primary site to another anatomic site. "We evaluated the correlation of EVI2B gene expression in metastatic melanoma samples with the IFN-γ related gene signature (CXCL10, CXCL9, HLA-DRA, IDO1, IFNG, and STAT1)." (PMID 34439264, 2021).
myocardial infarction (2 papers, 2024). Gross necrosis of the myocardium, as a result of interruption of the blood supply to the area, as in coronary thrombosis. "Coronary arteriosclerosis shared 10 GWS genes with AD (BAG6, C6orf10, HLA-DQB1, HLA-DRA, HLA-DRB1, NDUFAF6, NME7, PLCG2, PRRC2A, and TRIB1), while myocardial infarction shared three genes with AD (HLA-DRA, PHB, and RP11-81K2.1)." (PMID 39201500, 2024).
osteosarcoma (2 papers, 2020 to 2021). A usually aggressive malignant bone-forming mesenchymal neoplasm, predominantly affecting adolescents and young adults. "Some of these genes have been reported as biomarkers for osteosarcoma, while the role of HLA-DRA, MTIF2, MRPS7 and CDK20, should also be further systematically investigated based on actual diseased tissues or even cell lines and animal models." (PMID 32665038, 2020). "Apparently, HLA-DRA may have the “driving” function in osteosarcoma." (PMID 32665038, 2020). "VAMP8, A2M, HLA-DRA, SPARCL1, HLA-DQA1, APOC1 and AQP1 were identified continuously upregulating during the oncogenesis and metastasis of osteosarcoma." (PMID 32665038, 2020). "Hence, I have compared the prognostic gene set for osteosarcoma, Cox univariate and multivariate analysis showed that BACE2, ING2 ALOX5AP, HLA-DMB, HLA-DRA, and SPINT2 were not the independent prognostic factors for osteosarcoma." (PMID 33520450, 2021).
periodontitis (2 papers, 2022 to 2023). An acute or chronic inflammatory process that affects the tissues that surround and support the teeth. "HLA-DRA is also a hub DEGs in the process of normal brain ageing, frontotemporal dementia, and ageing periodontitis tissues." (PMID 37744379, 2023).
rosacea (2 papers, 2016 to 2018). A chronic erythematous skin disorder that affects the face. "The study identified an association between rosacea risk and a single nucleotide polymorphism (SNP) in the human leukocyte antigen (HLA) region located between HLA-DRA and BTNL2, which supported the concept of an inflammatory genetic component to rosacea." (PMID 29771307, 2018).
sarcoma (2 papers, 2019 to 2024). A usually aggressive malignant neoplasm of the soft tissue or bone. "Cell‐cell communication analysis showed that SD3 enriched sarcoma cell subtype sarco_2 had low expression of HLA‐DRA, HLA‐E, HLA‐F and HLA‐A, and high expression of ICAM1 and TGFB1." (PMID 39658531, 2024).
Sjögren’s syndrome (2 papers, 2024 to 2025). "In Sjögren’s syndrome, HLA-DRA was significantly upregulated in salivary gland epithelial cells." (PMID 39346909, 2024).
squamous cell carcinoma (2 papers, 2022 to 2024). A carcinoma arising from squamous epithelial cells. "This study aimed to evaluate the gene and protein expressions of CD74 and HLA-DRA in the progression from normal cervix to precancerous cervical intraepithelial neoplasia (CIN) and finally to squamous cell carcinoma (SCC)." (PMID 35208514, 2022).
vitiligo (2 papers, 2025). Generalized well circumscribed patches of leukoderma that are generally distributed over symmetric body locations and is due to autoimmune destruction of melanocytes. "Compared with the healthy controls, monocyte subpopulations expressed high levels of HLA-DRA, FOS, and the uncharacterized gene AC253572.2 in vitiligo patients." (PMID 41438750, 2025).
acute leukemia (1 paper, 2025). A clonal (malignant) hematopoietic disorder with an acute onset, affecting the bone marrow and the peripheral blood. "The results of our study suggest that the increased expression of ACTB and the molecular interplays involving “HBA1&HBB," “HBB&HBA1," “IGKV1-5&IGHV4-31," “IGHV4-31&IGKV1-5," “HLA-DRA&CD74" and “ACTB&ACTB" might contribute to the progression of acute leukemia." (PMID 40338916, 2025). "Furthermore, the suppression of ACTB and the molecular interactions involving pairs such as “HBA1&HBB", ”HBB&HBA1", “IGKV1-5&IGHV4-31", “IGHV4-31&IGKV1-5", “HLA-DRA&CD74", and “A CTB&ACTB" might provide essential insights into unraveling the intricate mechanisms of acute leukemia." (PMID 40338916, 2025).
adrenal cortical tumors (1 paper, 2022). "For instance, the expression level of HLA-DRA gene is associated with poor prognosis of adrenal cortical tumors in children." (PMID 35185791, 2022).
coccidioidomycosis (1 paper, 2024). A fungal infection caused by Coccidioides immitis. "Coccidioides immitis spherule (DB11294) is a binder of HLA-DRA used to detect the late-onset hypersensitivity to Coccidioides immitis in individuals with a history of pulmonary coccidioidomycosis." (PMID 38166628, 2024).
colorectal adenocarcinoma (1 paper, 2024). The most common type of colorectal carcinoma. "In addition, higher HLA‐DRA or IL1B expression levels also predicted good overall survival in kidney renal clear cell carcinoma (KIRC) and colorectal adenocarcinoma (COAD), respectively." (PMID 38483933, 2024).
cutaneous sarcoidosis (1 paper, 2023). "The class-II major histocompatibility complex factor HLA-DRA (human leukocyte antigen DR isotype) is a downstream effector of interferon-γ and TNF-α stimulations and has been recently implicated in granuloma formation in cutaneous sarcoidosis." (PMID 38067175, 2023).
dermatomyositis (1 paper, 2023). Dermatomyositis (DM) is a type of idiopathic inflammatory myopathy characterized by evocative skin lesions and symmetrical proximal muscle weakness. "However, in different muscular disorders, including polymyositis or dermatomyositis, HLA-DRA is upregulated in mononuclear inflammatory infiltrates and at the level of the sarcolemma and inside myofibers." (PMID 38067175, 2023).
epilepsy (1 paper, 2022). A brain disorder characterized by episodes of abnormally increased neuronal discharge resulting in transient episodes of sensory or motor neurological dysfunction, or psychic dysfunction. "Although epilepsy is not considered a primary immune-mediated disease, DRE microglial clusters 7, 5, 9 and 11 were characterized by high gene expression levels of TNF, HLA-DRA and HLA-DPB1 and low CX3CR1 and P2RY12 gene expression levels." (PMID 35739273, 2022).
Hepatitis (1 paper, 2023). Inflammation of the liver. "Notably, our study also found that the Turquoise module including hub gene HLA-DRA, displayed higher expression in NASH, which associated with NAFLD loci found by GWAS, and genetic variants of HLA−DRA has been recently reported to affect hepatitis development in a Korean population." (PMID 37008925, 2023).
IgA nephropathy (1 paper, 2026). "This study delivers a reproducible 9-gene machine-learning classifier for precise IgA nephropathy diagnosis and highlights HLA-DRA and VASH1 as promising biomarkers." (PMID 41803714, 2026).
Infertility (1 paper, 2024). "The results found polymorphic variants, associated with infertility, in the major histocompatibility complex, class II, DR alpha (HLA-DRA) gene: rs8084 and rs7192, which control spermatogenesis in men and are involved in cell adhesion and motility at the level of spermatocytes and spermatids." (PMID 38790168, 2024).
kidney cancer (1 paper, 2024). Primary or metastatic malignant neoplasm involving the kidney. "Nevertheless, studies on HLA-DRA in kidney cancer are limited and have mainly focused on bioinformatics analysis." (PMID 38931345, 2024).
medulloblastoma (1 paper, 2021). A malignant, invasive embryonal neoplasm arising from the cerebellum. "We also examined SHH-subgroup tumors stratified by age, irrespective of subtype; infant medulloblastomas showed significantly higher HLA-DRA, consistent with developmental differences producing differences in the TME, as in our model." (PMID 34021242, 2021).
mesothelioma (1 paper, 2023). A usually malignant and aggressive neoplasm of the mesothelium which is often associated with exposure to asbestos. "We report that the expression of ChemR23 coding gene, CMKLR1, in breast and mesothelioma tumors positively correlates to the expression of TAM markers such as CD14, CD163, MRC1 and HLA-DRA, in agreement with ChemR23 detection restricted to macrophages in tumors from patients." (PMID 37539056, 2023).
nodular sclerosis (1 paper, 2022). "In our study, genes related to major histocompatibility complex (MHC) class I and II machinery/biosynthesis such as HLA-DRA, CTSS, HLA-DPA1, HLA-DPB1, CTSC, B2M genes were expressed at higher levels in the mixed-cellularity subtype than in nodular sclerosis subtype at diagnosis." (PMID 36230815, 2022).
penicillin allergy (1 paper, 2020). "There is a previous GWAS on the immediate type of penicillin allergy, where a borderline genome-wide significant protective association of an allele of the MHC class II gene HLA-DRA was detected and further replicated in a different cohort." (PMID 32888428, 2020).
pulmonary edema (1 paper, 2019). Accumulation of fluid in the lung tissues causing disturbance of the gas exchange that may lead to respiratory failure. "Our finding was consistent with positive selection of HLA loci (HLA-DRA, HLA-DQB1/HLA-DQA2) in Ethiopian population and significantly associated with the high-altitude pulmonary edema of HLA-DR6 and HLA-DQ4." (PMID 31827636, 2019).
renal carcinoma (1 paper, 2024). A carcinoma arising from the epithelium of the renal parenchyma or the renal pelvis. "In this study, we found that cuproptosis induces the expression of HLA-DRA and, at the same time, that the expression of HLA-DRA is strongly correlated with the sensitivity to immunotherapy in renal cancer." (PMID 38931345, 2024). "The results demonstrated that HLA-DRA was expressed in both renal carcinoma and peritumoral tissues." (PMID 38931345, 2024). "Immunohistochemical (IHC) staining was used to analyze the expression of HLA-DRA in renal carcinoma and paracancerous tissues." (PMID 38931345, 2024).